TNF (tumor necrosis factor)
Diseases named in the same sentence as TNF in open-access papers (continued):
Sharing a sentence is not in itself a finding about the gene and the disease.
psoriasis (continued). "Psoriasis is an autoimmune disease with modest systemic aberrations of IL-6, CRP, TNF-α, E-selection, and ICAM and comorbidity with SCZ." (PMID 35082268, 2022). "Th1 cells increase the production of IL-2, TNF-α, and IFN-γ, participating in the development of psoriasis." (PMID 35126161, 2022). "IL-37 inhibits the IL-1β, IL-6, and TNF cytokines—which play fundamental roles in psoriatic inflammation—but it can also suppress some chemokines, such as CCL2, which is also important in psoriasis and rheumatic diseases." (PMID 34360845, 2021). "The function of regulation for a variety of inflammatory molecules such as TNFα, IL-6, MIP-1B, and iNOS has been reported, which also plays an important role in the pathogenesis of psoriasis." (PMID 34395618, 2021). "Epidermal keratinocytes respond to TNF-α, IL-17A, and IFN-γ, which are involved in the pathogenesis of psoriasis, in part by producing inflammatory cytokines, chemokines, and antimicrobial peptides." (PMID 34884474, 2021). "We further explored the expression of PI3K isoforms in response to IL-22, IL-17A, TNF-α, and IFN-γ, pro-inflammatory cytokines deeply involved in psoriasis pathogenesis." (PMID 34685616, 2021). "We obtained a psoriasis-like phenotype of HPK with a combination of physiological concentrations of IL-17A, IL-22 and TNF-α (20 ng/mL each)." (PMID 33801280, 2021). "AST-005, tested in collaboration with Purdue Pharma, knocks down a tumor necrosis factor (TNF), a pro-inflammatory cytokine demonstrated to be a key psoriasis mediator." (PMID 34684016, 2021). "In our study, there is downregulated expression of loricrin, filaggrin and involucrin, but elevated expression of keratin 5, keratin 14 and keratin 15 in IL-17A/IL-22/IFN-γ/TNF-α–induced HaCaT cells and in mice with IMQ-induced psoriasis." (PMID 34456715, 2021). "Previous studies have reported that several cytokines, including IL-17, IL-22, IL-23, and tumor necrosis factor-α (TNF-α), are expressed highly in the epidermis of patients with psoriasis or the imiquimod-induced mouse model." (PMID 34281197, 2021). "Here, we investigated the effect of cudraxanthone D (CD), extracted from the roots the C. tricuspidata Bureau, on psoriasis using an imiquimod (IMQ)-induced mouse model and the tumor necrosis factor (TNF)-α/interferon (IFN)-γ-activated keratinocytes." (PMID 34641629, 2021). "The present study showed that alantolactone decreased the mRNA levels of TNF-α, IL-6, IL-1β, IL-8, IL-17A, and IL-23, thereby suppressing Th1- and Th17-mediated cytokines and improving IMQ-induced psoriasis-like skin lesions and inflammation status in mice." (PMID 34202301, 2021). "Given that TNF-α synergizes with IL-23 to promote IL-17A production by ILCs, it is likely that TNF-α and IL-23 inhibition are effective for psoriasis at least in part due to their ILC3 suppressive effects, thereby reducing IL-17A." (PMID 33749662, 2021). "Several angiogenic mediators such as VEGF, HIF-1α, the Angs, and the pro-angiogenic cytokines (including tumor necrosis factor [TNF], interleukin [IL]-8, and IL-17) are upregulated during psoriasis development." (PMID 34769465, 2021). "The deletion of Treg cells in mice with imiquimod induced psoriasis phenotypes leads to increased infiltration of γδ, CD4+ and CD8+ T cells, the increased presence of IL-17 and TNF-α, as well as increased severity of skin lesions." (PMID 34639182, 2021). "The data of the nation, age, interval, rate of psoriasis in IBD, gender, rash distribution, smoke history, type of TNF-antagonist, and medication condition were collected." (PMID 34678884, 2021). "RT-PCR analysis showed that the mRNA levels of IL-23 P19, TNF-α, CXCL2 and S100A8 were significantly attenuated in back skin from IMQ-induced psoriasis mice." (PMID 34381369, 2021).
psoriasis (continued). "Additionally, several cytokines, such as tumor necrosis factor (TNF)-α, interleukin (IL)-1β, IL-12, IL-17A, IL-22, and IL-23, upregulate the production of reactive oxygen species and the hyperproliferative keratinocyte state seen in psoriasis, and are shown to play a role in some malignancies." (PMID 34685480, 2021). "Keratinocytes react with pro-inflammatory cytokines such as TNF-α and IFN-γ, which are involved in the expression of many inflammatory mediators during chronic inflammatory skin disorders, such as psoriasis and AD." (PMID 34575836, 2021). "TNF is known to be negatively regulated by IFNI in chronic inflammatory diseases, including psoriasis." (PMID 34298932, 2021). "The tumor necrosis factor-alpha (TNF-α)/IL-23/IL-17A axis plays a key role in induction and progression of psoriasis; thus, biological drugs against TNFα/IL-23/IL-17A have good therapeutic efficacy." (PMID 33499346, 2021). "The best-known member of the TNF/TNFR family is TNFα, which mainly plays a crucial role in autoinflammatory diseases (i.e., psoriasis, inflammatory bowel disease, spondylo-arthritis)." (PMID 33467204, 2021). "Psoriasis patients exhibit enhanced circulating levels of IL-6, IL-18, IL-17A, IFN-γ, TNF, IL-1β, IL-27 and IL-29." (PMID 34068473, 2021). "This study was performed to observe the effects of FZHFZY on epidermal differentiation in IL-17A/IL-22/IFN-γ/TNF-α stimulated HaCaT cells and a mouse model of IMQ-induced psoriasis." (PMID 34456715, 2021). "In mouse model of psoriasis, NLRP3 inflammasome keratinocytes can be activated by TNF-α to induce inflammation, which was induced by inhibiting autophagy via PI3K/AKT/mTOR signaling pathway." (PMID 34707607, 2021). "Although anti–TNF-α therapy appears to increase the weight and BMI of patients, this effect does not appear in patients treated with anti–IL-12/23 therapy with weight-adjusted doses, suggesting that ustekinumab could be considered to treat overweight and obese patients with psoriasis." (PMID 34803716, 2021). "A total of 2228 patients were included (median age 43.3 years, 57% female), of which 52% (n = 1155) received TNFα‐i for RD, 43% (n = 967) for IBD, and 5% (n = 106) for psoriasis." (PMID 34302442, 2021). "Several cytokines are used for the generation of psoriasis-like HPK, i.e., IL-17A, TNF-α, IL-36γ, oncostatin, IFN-γ, IL-22 and IL-1α." (PMID 33801280, 2021). "Furthermore, four out of six rSNPs uncovered by SNPClinic v.1.0 software, could also be validated in the clinic as companion diagnostics/pharmacogenetics assays for psoriasis prescribed drugs that block TNF-α (e.g. Etanercept), IL-17 (e.g. Secukinumab) and IL-17 receptor (Brodalumab)." (PMID 33898962, 2021). "A fact which must also be taken into consideration is that psoriasis keratinocytes exhibit immunity to signals transmitted by TNF-α, which results in an increase in TNF-α concentration in skin alterations as well as serum in patients with psoriasis." (PMID 33562571, 2021). "TNF-α promotes the differentiation of Th22 cells, while TNF-α blockade has achieved satisfactory results in the treatment of psoriasis patients." (PMID 34295334, 2021). "In studies of patients with psoriasis, the supply of these bacteria resulted in a decrease in CRP and the pro-inflammatory cytokine TNFα in the serum of patients." (PMID 33924414, 2021). "PPPs altered the mRNA expressions of the inflammatory cytokines (TNF-α, IL-6, and IL-1β) and improved the expressions of AQP3 and FLG in psoriasis-like mouse skin." (PMID 35153762, 2021). "A total of 389 significant genes were common to both hepatitis C and psoriasis, which mainly involved IL6, TNF, IL10, ALB, STAT3 and CXCL8." (PMID 34215260, 2021). "However TNFα has been shown to inhibit the following: the secretion by plasmacytoid dendritic cells (pDC) of interferon gamma (IFNγ—an immunoregulatory cytokine that induces the release of inflammatory cytokines), the proliferation of KCs, and the maintenance of psoriasis." (PMID 34691360, 2021).
psoriasis (continued). "Psoriasis, both vulgaris and arthritic, as well as SLE and RA, have higher expression of NF-κβ and TNF-α, which is the product of its activity." (PMID 33450863, 2021). "To pace into our ultimate goal for developing OXY as a potential treating agent for psoriasis, we therefore focused mainly on exploring the anti-proliferative effects of OXY against TNF-α stimulation in keratinocyte, using HaCaT as a study model." (PMID 35056961, 2021). "The expression of HMOX1 can be induced by a variety of stimuli, including the proinflammatory cytokines TNF and IL17, which are abundant in the lesional skin of psoriasis patients." (PMID 34575702, 2021). "Glycyrrhizin is a therapeutic substance that improves psoriasis by down-regulating IL-17A and INF-γ, and further inhibits the expression of IL-6, TNF-α, and CCL20 induced by IL-17A." (PMID 34044769, 2021). "When keratinocytes are stimulated by TNF-α, IFN-γ, IL-22 and IL-17A, they can express the inflammatory marker proteins related to psoriasis, such as chemokines and proinflammatory cytokines." (PMID 34456715, 2021). "Psoriasis pathogenesis is induced by melanocyte presentation of autoantigens to autoreactive epidermal CD8+ T cells, which determine increased levels of TNF-α, IL-17, and Il-17/IL-23." (PMID 34441010, 2021). "TNF-α can help promote the development of psoriasis, and the therapeutic effect of TNF-α inhibitors on psoriasis has confirmed this conclusion." (PMID 33975513, 2021). "Pro-inflammatory cytokines, including TNF-α, play a crucial role in pathogenesis of both NAFLD and psoriasis, as well as in the progression of NAFLD to non-alcoholic steatohepatitis (NASH)." (PMID 33883616, 2021). "IL17A and TNFα, the key genes of the TNFα/IL23/Th17 axis in psoriasis, were significantly upregulated in psoriasis skin samples compared to healthy samples." (PMID 33807762, 2021). "Treatment of human keratinocytes with IL17A, TNF-α and IL-22 upregulates KRT17 by the transcription factor STAT3 that is constitutively phosphorylated in psoriasis." (PMID 33801280, 2021). "For their good safety profile and high sustainability, TNF-α inhibitors have revolutionized the management of numerous chronic immune-mediated inflammatory diseases, including IBD and psoriasis." (PMID 33114187, 2020). "TNF-α and IFN-γ are well known as inducers of inflammation in psoriasis, which can also be considered as apoptosis inducers." (PMID 32632545, 2020). "LP and psoriasis show a similar pathological background, including features of skin barrier dysfunction, T lymphocyte activation, and upregulation of cytokines such as tumor necrosis factor (TNF)-α, interleukin (IL)-6, IL-10, and IL-4 and may therefore be associated with a high risk of MS." (PMID 32822406, 2020). "TNF‐α positivity of circulating CD3+ cells was instead lower only in patient 1, as compared to patient 2 and patients with classical psoriasis." (PMID 31577850, 2020). "Statistical analysis of qRT-PCR results indicated that the mRNA expression of Arg-1, TNF-α, PD-1, PD-L1, ROR-γ, and IL-10 in the PBMCs of psoriasis patient group was significantly different from expression levels of the control group." (PMID 32382290, 2020). "As the prominent cellular source of IFNα, TNFα, IL12, and IL23, DCs play an important role in psoriasis." (PMID 33050592, 2020). "In patients with psoriasis, frequency of circulating CD20+ T cells producing IL-17, IL-21, and TNFα correlates with disease activity." (PMID 33628202, 2020). "Therefore, TNF-α antagonists might exert effects on psoriasis via this pathway." (PMID 32280718, 2020). "As expected, TNF-α (P < 0.05) and IFN-γ (P < 0.05) were significantly elevated in the lesions of psoriasis compared with HC by RT-qPCR." (PMID 32632545, 2020).
psoriasis (continued). "Here, we demonstrated that TNFAIP3 mRNA was expressed at low levels in psoriatic patients and the IMQ-induced psoriasis-like dermatitis model and that TNF-α antagonists increased TNFAIP3 expression and attenuated the severity of psoriasis in the mouse model." (PMID 32280718, 2020). "A negative correlation was demonstrated between plasma adiponectin levels and both the Psoriasis area and severity index (PASI) score and plasma TNF-α levels in psoriatic patients." (PMID 32823524, 2020). "mRNA expression of Arg-1, TNF-α, PD-L1, and ROR-γ was increased, while the expression of PD-1 and IL-10 was decreased in the PBMCs of psoriasis patients." (PMID 32382290, 2020). "PP is generally reported during anti-TNF-α treatment, such as infliximab and adalimumab, in diseases for which anti-TNF-α treatment is indicated, particularly IBD and psoriasis." (PMID 33114187, 2020). "Compared with healthy controls, the mRNA expression of Arg-1, TNF-α, ROR-γ, and PD-L1 was increased, while the mRNA expression of PD-1 and IL-10 was decreased in PBMCs from psoriasis patients." (PMID 32382290, 2020). "Immune-related cells such as dendritic cells (DCs) and macrophages, in addition to Toll-like receptors and cytokines such as interferon (IFN)α, TNFα, IFNɤ, IL12, IL22, IL23, and IL17, are related to the pathogenesis of psoriasis." (PMID 33050592, 2020). "In contrast to classical psoriasis, psoriasiform lesions of HS patients showed a reduced number of IFN‐γ and TNF‐α‐releasing T lymphocytes." (PMID 31577850, 2020). "Clinical skin severity was assessed with the psoriasis area index (PASI), whilst ELISA detected the expression of TNF-α, IL-17A, and IL-22." (PMID 33253155, 2020). "The purpose of this study is to compare CVR in psoriasis patients receiving two types of treatments: methotrexate (MTX) and tumor necrosis factor inhibitor (TNF-i) and to evaluate the correlation between the Framingham score and QIMT." (PMID 32122693, 2020). "TNF-α is a classical pro-inflammatory cytokine that has been proven to be an efficacious therapeutic agent in a variety of diseases, such as RA, IBD, and psoriasis." (PMID 32636750, 2020). "IL-1β, IL-6 and TNF-α are important proinflammatory cytokins, especially TNF-α, involving in psoriasis pathogenesis." (PMID 33081840, 2020). "Previous findings demonstrate an increased expression of tumor necrosis factor (TNF)-α, nuclear factor-kappa B, IL-6, and IL-8 in psoriasis-affected nails." (PMID 32759698, 2020). "We found that the mRNA expression of Arg-1, TNF-α, ROR-γ, and PD-L1 was increased, while that of PD-1 and IL-10 mRNA was decreased in the PBMCs of psoriasis patients group." (PMID 32382290, 2020). "In clinical trial SPIRIT-P2, IXE improved the signs and symptoms of patients with active PsA (inadequate responders to tumor necrosis factor [TNF] inhibitor) along with a safety profile consistent with previous studies involving both PsA and psoriasis." (PMID 31964419, 2020). "For maintenance of Th17 cells, IL-23 is required and secreted from inflammatory DCs or TNF-α and iNOS-producing DCs (TIP-DCs) Psoriasis and other Th17-mediated skin diseases." (PMID 33633737, 2020). "We also observed that TNF-α and IFN-γ mRNA expression levels in lesions of psoriasis were increased, consistent with other reports." (PMID 32632545, 2020). "The gene expression of TNF, IL23, and IL17A is upregulated in the skin lesions of psoriasis patients." (PMID 31936670, 2020). "In a psoriasis mouse model, curcumin significantly inhibited secretion of inflammatory factors including interleukin (IL)-17, IL-22, IFN-γ, IL-2, IL-8 and TNF-α in T cells by 30%–60% in vitro." (PMID 32143311, 2020). "Increased levels of TNF-α, IL-2, and INF-γ, as well as decreased content of IL-10 in NWS and SWS of psoriasis patients compared to the controls indicated an imbalance between Th1 and Th2 cells in the salivary glands." (PMID 32164227, 2020).
psoriasis (continued). "IL17 is produced, as well as TNF, IL26, and IL29 (IFNλ1), under specific situations such as psoriasis autoantigens and/or certain environmental stimuli (e.g., trauma or infection)." (PMID 33050592, 2020). "SFAs, red meat, simple sugars, or alcohol exacerbate psoriasis and its comorbidities via the activation of NLRP3 inflammasome cascade or TNF-α/IL-23/IL-17 axis, generation of ROS, prostanoids/LTs, gut dysbiosis or suppression of Tregs." (PMID 32751360, 2020). "The concentration of TNF-α (↑19.77%, p = 0.0002) and IL-2 (↑15.54%, p = 0.03) in SWS of patients with hyposalivation was considerably higher than in psoriasis patients with normal saliva secretion." (PMID 32164227, 2020). "The recent therapeutic success of anti-tumour necrosis factor (TNF)-α and anti-IL-17 antibodies has emphasized the critical roles of TNF-α and IL-17A in psoriasis development." (PMID 32194991, 2020). "Many inflammatory cytokines, such as tumor necrosis factor-α (TNF-α), interleukin- (IL-) 17, IL-1, were elevated in the skin of psoriasis." (PMID 32090080, 2020). "The positive staining for both TNF-α and IL-1β was increased in the IMQ group in comparison to the normal group, indicating high expression of pro-inflammatory cytokines in psoriasis plaque." (PMID 32708987, 2020). "By analogy to Sjögren’s syndrome, the observed increases in TNF-α, IL-2, and INF-γ concentrations allow us to assume that salivary glands of patients with psoriasis are infested with autoreactive Th1 lymphocytes." (PMID 32164227, 2020). "KEGG pathway enrichment analysis revealed that the inflammatory-related signaling pathways such as NF-κB, TLR, TNF, and IL-17 were significantly activated in the IMQ-induced psoriasis mouse model." (PMID 32398953, 2020). "By mid-2020, more than 14 biologics (tumor necrosis factor-alpha blocker, interleukin-12/23 and interleukin-17 inhibitors) have been approved by the FDA for adult psoriasis." (PMID 32953323, 2020). "Taken together, our data provides evidence that the percentage of CD14+HLA-DR−/low MDSC/ CD14+ cells and TNF-α and FOXP3 mRNA expression levels in PBMCs are potential biomarkers for making a distinction between the psoriasis TCM BS syndrome and BH syndrome." (PMID 32382290, 2020). "The pathophysiology of PsA and psoriasis is shared as synovial tissue in psoriatic arthritis expresses pro-inflammatory cytokines: IL-1, IFN-γ, and TNFα." (PMID 30909615, 2019). "The rational for treatment with biological agents is given through significant overexpression of Il-17A, TNF-α, IL-1, IL-36 in GPP and in psoriasis." (PMID 31286990, 2019). "However, there is ample evidence in the literature that the intrinsic defect in psoriasis may lie well within the psoriatic skin, with the overproduction of inflammatory mediators such as TNFα triggering and perpetuating inflammatory reactions, independent of autoreactive T cells." (PMID 31357710, 2019). "In accord with the general role of TNF-α as a stimulatory cytokine, treatment with the potent TNF-α-inhibitor infliximab rapidly reduced IL-12, IL-1β, and CCL20 mRNA expression in psoriasis patients." (PMID 31191513, 2019). "Upon DAMP or PAMP stimulation, keratinocytes are capable of producing an array of proinflammatory cytokines, such as IFNβ, IL1β, IL36, TNF, IL6, IL8, IL25, and CXCL10, to initiate the inflammatory T cell phenotype in psoriasis." (PMID 31815151, 2019). "It was the first TNF-α inhibitor approved by the United States Food and Drug Administration (FDA) for psoriasis." (PMID 30909615, 2019). "The pathophysiology of psoriasis involves activation of dendritic cells, neutrophils, and T cells, mainly CD8+, with consequent production of IL-8, TNF-α, and IL-17." (PMID 31789260, 2019). "6-Sulfo LacNAc-expressing monocytes were previously identified as IL-23-, TNF-α-, and iNOS-expressing inflammatory dermal DCs in psoriasis and thus are part of the population of inflammatory dermal DCs (TIP-DCs) in psoriasis." (PMID 29977237, 2018).